CRP (C-reactive protein)
Diseases named in the same sentence as CRP in open-access papers (continued):
Sharing a sentence is not in itself a finding about the gene and the disease.
depression (continued). "Previous investigations have reported a decrease in depressive manifestations after a weight loss treatment, however, this study specifically demonstrates a relationship of the decrease in CRP and leptin with the reduction in self-perceived depression in subjects suffering MetS." (PMID 24762259, 2014). "A number of studies in various populations have reported correlations between depression and inflammatory markers, such as C-reactive protein and interleukin(IL)-6, thus giving rise to the “inflammatory hypothesis of depression”." (PMID 25153995, 2014). "CRP levels are known to be increased in patients suffering from depression or anxiety disorders." (PMID 25007072, 2014). "Notably, increased CRP levels have been used previously to predict depression severity and recurrence rates in males." (PMID 24782789, 2014). "Hassin-Baer and colleagues investigated the association of CRP levels and non-motor symptoms in PD, and demonstrated that CRP levels were associated with depression but not with psychosis." (PMID 24497930, 2014). "Depression is often characterized with high levels of C-reactive protein (CRP), which may contribute to cardiovascular disease development in depressed patients without somatic diseases." (PMID 24170724, 2013). "Major depressive disorder (MDD) is a complex illness associated with immune system involvement and a systemic inflammatory response, including elevated C-reactive protein (CRP) and plasma immunomodulatory cytokine levels." (PMID 24222882, 2013). "Because increased levels of CRP predict the subsequent risk for de novo depression, these findings suggest that the documented immune findings are not merely epiphenomena of depression, but actually contribute to the genesis of the disorder." (PMID 23506529, 2013). "Additionally, South Asians had more prominent abnormalities in fibrinogen, plasminogen activator inhibitor 1, homocysteine, C-reactive protein, insulin sensitivity, and psychosocial factors (stress, depression)." (PMID 24163770, 2013). "In addition, preliminary findings suggest a relationship between depression, markers of inflammation (such as IL-6 and CRP), and telomere length." (PMID 23691300, 2013). "Although the number of patients classified as suffering atypical depression is relatively low, these patients may be more likely to show high levels of inflammatory markers such as CRP." (PMID 24385966, 2013). "Depression also has been linked to increased levels of cytokines (specifically CRP, IL-1, and IL-6), both in patients with and without a history of cardiac disease." (PMID 23653854, 2013). "Some earlier studies have shown the probable mechanism of CRP rise in depression." (PMID 21701640, 2011). "Despite a large number of studies linking depression and anxiety to elevated CRP level, so far there has been only two studies investigating CRP genetic variants in depression, and none investigating these CRP variants and the metabolic syndrome in those with affective symptoms." (PMID 21296145, 2011). "In newly diagnosed patients of depression, inflammatory markers such as CRP, ESR and WBC count were significantly raised and Selective serotonin reuptake inhibitors SSRIs such as fluoxetine and escitalopram reduced them independent of their antidepressant effect." (PMID 21701640, 2011). "CRP has also been associated with long-term stress as well as with depression but data is not consistent." (PMID 19888340, 2009). "There is strong clinical evidence in subgroups of patients with depression that symptom intensity and the course of disease are associated with elevated plasma levels of pro-inflammatory mediators, including IL-1, IL-2, IL-6, TNF, and C-reactive protein." (PMID 19936105, 2009). "The relationship between depression and panic disorder on the one hand, and elevated levels of CRP on the other, is rendered even more important given the well-established but as yet unexplained relationship between these two disorders and cardiovascular morbidity." (PMID 18384670, 2008).
depression (continued). "Moreover, ML identified CRP as the most important predictor of depression." (PMID 40851223, 2026). "In addition, an interim analysis from an ongoing randomized placebo-controlled study with enoxolone, 100 mg vs. placebo, in hospitalized patients with depression, confirmed target engagement by a significant reduction in the night urine aldosterone/cortisol ratio and of plasma CRP." (PMID 41155634, 2025). "The third significant finding of this study is that the severity of the physio-affective phenome of Long COVID disease, as defined by CFS, depression, and anxiety symptoms, could be significantly predicted by IgA/IgG/IgM responses against neuronal proteins, and increased serum CRP and AOPP levels." (PMID 39522688, 2025). "Patients with depression often exhibit dysregulated levels of inflammatory markers; for instance, those with metastatic lung cancer combined with depression may have elevated C-reactive protein (CRP) levels and an increased CRP/albumin ratio." (PMID 40110200, 2025). "A recent investigation analyzing the correlation between age and CRP within a psychiatric inpatient population found comparable shifts in sex-specific CRP concentrations among patients diagnosed with schizophrenia spectrum disorder and those with unipolar depression." (PMID 40980040, 2025). "In addition, higher cerebrospinal fluid (CSF) levels of C-reactive protein (CRP) and monocyte chemotactic protein-1 (MCP-1) have been associated with more severe fatigue, depression, and cognitive impairment in PD, supporting the role of central inflammation in these overlapping symptoms." (PMID 41211291, 2025). "In contrast, responders with CRP < 1 mg/L have not only inhibition of immunometabolic pathways but also activation of the oxytocin signalling pathway, which has several anti-inflammatory properties and has been investigated as a potential therapeutic target in depression." (PMID 39271754, 2025). "Therefore, IL-6, CRP, and TNF-α may represent promising targets in research on the pathomechanisms of depression and in the search for new diagnostic strategies." (PMID 40507778, 2025). "Importantly, some studies suggest bidirectional relationships: Das found elevated CRP predicted future depression and stress, indicating CRP may function as both marker and mediator of psychosocial burden." (PMID 40514590, 2025). "Furthermore, we hypothesized that individuals with higher CRP levels across the measurement waves would report higher depression scores across measurement waves, and vice versa." (PMID 41661985, 2025). "A subset (n = 29) of the present TRD sample (n = 40) was previously included in a study that examined whether changes in inflammation occur over the course of ECT (T1, T2 and T3) and whether changes in IL-6 or CRP (from T1 to T2) predicted global improvement in depression severity." (PMID 39834556, 2025). "Indeed, when specifically examining the link between CRP and depression, a recent meta-analysis that examined 56 studies found that in most studies a positive association existed between elevated CRP levels and depression and that CRP levels tend to be associated with depressive severity." (PMID 41661985, 2025). "PerspectiveThis study provides insight into potential underlying pathophysiological process of pain-type somatic symptoms, by showing that C-reactive protein may be associated with pain-type somatic symptoms, independent of anxiety or depression score." (PMID 40823322, 2025). "For example, in PsA, depression has been associated with serum IL-6, but not IL-17A or CRP." (PMID 39959848, 2025). "Their review highlighted that both innate and adaptive immune dysregulation in major depressive disorder (MDD) lead to persistent elevation of CRP and IL-6, promoting microglial activation and impaired synaptic plasticity, which hypothetically could hinder the response to antidepressants." (PMID 41373439, 2025).
depression (continued). "Studies on the related mechanisms have found that patients with anxiety or depression may exhibit elevated levels of inflammatory markers (such as CRP), altered platelet aggregability, and reduced sympathetic nerve activity, which can lead to an increased rate of MACE." (PMID 40365002, 2025). "Depression, for instance, may accelerate cancer progression through endocrine and immunological changes, particularly chronic inflammation, with increased production of interleukin-6 (IL-6), C-reactive protein and TNFalpha." (PMID 39754194, 2025). "Therefore, CRP may be more strongly related to depressive symptoms in the context of major depression, whereas other inflammatory molecules, such as IL-6, may be related to depressive symptoms regardless of whether someone is presently experiencing depression." (PMID 40357904, 2025). "Additionally, chronic insomnia may exacerbate emotional vulnerability, intensifying the interplay between anxiety and depression symptoms and the inflammatory marker CRP." (PMID 41048872, 2025). "Furthermore, AGP had a stronger predictive effect on depression compared to CRP." (PMID 40530060, 2025). "However, patients with recurrent UC presented a longer disease course, higher baseline levels of CRP and calprotectin, more pronounced anxiety and depression, greater severity of fecal incontinence, and lower BMI, Hb, ALB, and IBD-Q scores than did those with newly diagnosed UC (all P < 0.05)." (PMID 39009899, 2024). "The mechanisms underlying anxiety and depression following TBI are currently unclear, but inflammation post-TBI is speculated to be a contributing factor, associated with elevated levels of TNF-α, IL-6, IFN-α, and CRP." (PMID 39554848, 2024). "Chronic inflammation, often characterized by elevated levels of C-reactive protein (CRP), has been associated with increased symptoms of depression and anxiety, suggesting that the management of inflammation may be an important component of psycho-oncology care." (PMID 39338146, 2024). "This type of depression is linked to increased pro-inflammatory cytokines such as interleukin 6 (IL-6), tumor necrosis factor alpha (TNF-α), C-reactive protein (CRP), and several other factors, and these inflammatory factors may help distinguish between inflammatory and non-inflammatory depression." (PMID 38589368, 2024). "Research findings also indicate that both major depression and depressive symptoms are associated with elevated serum concentrations of inflammatory mediators, including acute-phase proteins such as CRP and fibrinogen, and these findings are not restricted to older age groups." (PMID 38575920, 2024). "High CRP levels in hemodialysis patients with depression may be due to various reasons." (PMID 38255209, 2024). "First, elevated post-stroke serum CRP levels might directly precipitate depression." (PMID 38377025, 2024). "Interestingly, depression symptoms did not correlate significantly with delirium or insomnia but exhibited significant associations with serum CRP levels, TBI classification, and self-efficacy." (PMID 39554848, 2024). "Interestingly, increased concentrations of inflammation markers, such as CRP, may be used as predictors of depression onset." (PMID 39519542, 2024). "As a result, our study only confirmed the association between hs-CRP levels and depressive symptoms and could not establish a relationship with depression." (PMID 38596631, 2024). "This biomarker shows robust associations with several clinical (i.e., somatic symptoms, fatigue, depression severity, quality of life) and cognitive (i.e., psychomotor speed) outcomes and performs well in comparison to single inflammatory proteins, like IL-6, CRP, and sIL-6R." (PMID 38442505, 2024).
depression (continued). "Additionally, our reanalysis of available data contributes to the existing body of evidence, revealing suggestive evidence with low bias that support the association between inflammatory biomarkers, such as C-reactive protein (CRP), and depression in patients with type 2 diabetes (class III)." (PMID 38617916, 2024). "Secondly, owing to the cross-sectional design of the analysis, our study could not indicate a causal relationship between hs-CRP and depression." (PMID 38596631, 2024). "In non-genetic analyses, higher CRP was associated with diagnosis of any depressive disorder, positive and negative affect scores, figural fluency, attention, and psychomotor speed after adjusting for potential confounders, although the magnitude of these associations was generally small." (PMID 38699368, 2024). "The relationship between sleep disturbance and depression might be explained in light of the inflammation hypothesis which highlights an association between poor sleep quality, increased levels of inflammatory cytokines such as interleukin-6 and C-reactive protein, and depression." (PMID 37069886, 2023). "Together with the existing contradictions in the literature on the role of CRP in depression, these findings suggest that CRP may not reliably influence HIV-associated depression." (PMID 37693812, 2023). "High levels of pro-inflammatory cytokines, such as IL-6, CRP, cortisol, and cerebral white matter lesions in patients with depression and frailty may adversely affect each other, leading to an increased risk of cerebrovascular disease, decreased activities of daily living, and mortality." (PMID 36780484, 2023). "Furthermore, increased plasma levels of C-reactive protein (CRP), a nonspecific marker of inflammatory processes, has been associated with increased levels of glutamate in the caudate of individuals with depression." (PMID 37182555, 2023). "There was no clear evidence of causality between genetically predisposed RC and HDL-C, BMI, circulating CRP, fasting blood glucose, fasting blood insulin, hip circumference, waist circumference, WHR, alcohol consumption, smoking status, overweight, HOMA-IR, insomnia, sleep apnoea, or depression." (PMID 37563569, 2023). "A segment of depression patients exhibits chronic inflammation, shown by increased systemic levels of inflammation-related markers, including cytokines and other inflammatory mediators, such as C-Reactive Protein (CRP), which have been correlated with more severe depression symptoms." (PMID 37575572, 2023). "Therefore, a sample capturing both extreme CRP concentrations and a severe depression phenotype may provide further clarification." (PMID 36712567, 2023). "Indeed, high levels of pro-inflammatory cytokines like interleukin-6 (IL-6), tumor necrosis factor-α and interleukin-1β (IL-1β), may promote the onset of depression, as well as inflammatory markers like C-reactive protein (CRP)." (PMID 37587401, 2023). "However, till date the association of CRP and IL-6 with depression and cardiometabolic risks in GDM has not been studied." (PMID 37365247, 2023). "In the present study, based on the important role of both mitochondrial function and inflammatory in mental disorders, we propose the hypothesis that genetic variations in mtDNA interacted with inflammatory markers (measured by CRP) has important implications for anxiety and depression." (PMID 37344456, 2023). "Factors like endothelial dysfunction, elevated C-reactive protein (CRP), platelet dysfunction, and reduced flow-mediated vascular dilation, which leads to accelerated atherosclerotic plaque formation in coronary artery disease (CAD) patients, are clearly linked to depression." (PMID 36628002, 2023).
depression (continued). "In a previous study, a correlation was established between depression and elevated levels of proinflammatory cytokines, including interleukins and tumor necrosis factor, as well as increased expression of inflammatory molecules, as measured via acute phase proteins, including the C-reactive protein." (PMID 38137013, 2023). "Third, CRP-depression may only exist in people living with atypical depression rather than melancholic depression, which reflects that depression subtypes may have unique but different biological pathways." (PMID 36860788, 2023). "In conclusion our findings do not support a major causal role of serum CRP on anxiety and depression symptoms and life satisfaction, but provide weak evidence that serum CRP may modestly decrease life satisfaction and increase anxiety and depression symptoms." (PMID 37217205, 2023). "Studies have shown that inflammatory factors IL-1β, IL-6, TNF-α, and CRP are elevated and anti-inflammatory factors IL-4, IL-8, and IL-10 are decreased in peripheral and cerebrospinal fluid and correlate with patients’ symptoms and disease duration in depression and anxiety." (PMID 36624089, 2023). "Since the important role of ROS in depression and anxiety, as well as the associations between ROS and inflammatory, based on these phenomena, it is plausible that the interaction between MT-ND1 and MT-ND2 and CRP may occur by acting on ROS for mood disorders." (PMID 37344456, 2023). "For every 1 mg/dL increase in serum magnesium, depression score reduction was greater in the subgroup with CRP levels ≥ 5 mg/L (0.56 in the crude model, 0.54 in Model 1, 0.50 in Model 2) than in the subgroup with CRP levels ≥ 3 mg/L (0.46 in the crude model, 0.41 in Model 1, 0.38 in Model 2)." (PMID 37049401, 2023). "Indeed, a recent cross-sectional study of almost 50,000 adults aged 18 to 93 found that depression and C-reactive protein (CRP, a commonly used inflammatory marker) both independently and jointly predicted poorer performance on the Ruff figural fluency test, a measure of executive function." (PMID 37686689, 2023). "Our results do not support a major causal role of serum CRP on anxiety and depression symptoms and life satisfaction, but provides weak evidence that serum CRP may modestly increase anxiety and depression symptoms and reduce life satisfaction." (PMID 37217205, 2023). "Furthermore, sleep deprivation has been demonstrated to further contribute to the onset and progression of depression through activation of the sympathetic nervous system and β-adrenergic signaling, which increased the level of inflammatory markers such as IL-6 and C-reactive protein." (PMID 37731854, 2023). "In the active rTMS group, the serum levels of CRP-hc and IL-2 significantly changed at week 2, and the change last through the 12 weeks period, which were not seen in the sham-rTMS group, suggesting that rTMS can change serum inflammatory cytokine levels in patients with depression." (PMID 35722555, 2022). "A combination of elevated IL-6, TNF-α, and CRP provided preferable prediction performance in terms of AUC (0.83) over individual biomarkers, with considerable sensitivity (78.5%) and specificity (77.9%) for depression, but it demanded higher costs and additional time." (PMID 35757220, 2022). "Chronic inflammation may induce the development of atherosclerosis and arterial thrombosis, and elevation in inflammatory biomarkers (i.e., IL-6 and C-reactive protein) has been reported in various psychiatric disorders including post-traumatic stress disorder and major depression." (PMID 36269046, 2022). "Finally, the slight increase in C-reactive protein and fecal calprotectin may indicate the participation of bacterial and inflammatory factors in the pathogenesis of depression." (PMID 35956393, 2022). "CRP blood levels and genome CRP SNPs were evaluated in 60 MDD patients with family depression history and 60 healthy control volunteers." (PMID 35163538, 2022).